TNF (tumor necrosis factor)
Diseases named in the same sentence as TNF in open-access papers (continued):
Sharing a sentence is not in itself a finding about the gene and the disease.
endothelial dysfunction (continued). "Once in the adipose tissue, macrophages produce pro-inflammatory cytokines, including interleukin (IL)-6, IL-1β, and tumor necrosis factor-alpha (TNF-∝) that alter adipose function and induce endothelial dysfunction even after total HIV viral suppression." (PMID 32880756, 2020). "For instance, pro-inflammatory metabolites (such as NO-related molecules), cytokines (including IL-1β, TNF-α, IFN-γ, IL-4, IL-5, IL-8, G-CSF, and MIP-1b), and markers of endothelial dysfunction (e.g., homocysteine) were found to be increased in VaD patients." (PMID 32340195, 2020). "Here we propose a model in which CX3CR1+ CD8 T cells promote endothelial dysfunction by the combined effects of CX3CL1, IL-15, and TNF." (PMID 32976527, 2020). "High levels of serum inflammatory cytokines and markers such as tumor necrosis factor-α (TNF-α), interleukin-6 (IL-6), C-reactive protein (CRP), and alpha-1-acid glycoprotein (AGP) have been correlated with the endothelial dysfunction." (PMID 31737180, 2019). "Markers of inflammation (IL-6, TNF-α, CRP), innate defense (cathelicidin), monocyte and macrophage activation (sCD14, sCD163 and, IL-2sRα), endothelial dysfunction (ET-1) and general immune health (CD4/CD8 ratio) were associated with lung abnormalities in HIV." (PMID 31830103, 2019). "Pro-inflammatory T cell–derived cytokines such as IFN-γ and TNF-α (from CD8+ and CD4+Th1) and IL-17A (from the γδ-T cell and CD4+Th17) exacerbate hypertensive responses mediating both endothelial dysfunction and cardiac, renal, and neurodegenerative injury." (PMID 31321561, 2019). "Nevertheless, no changes were observed in the concentrations of markers related to endothelial dysfunction [VCAM, E-selectin, and advanced glycation endproducts (AGEs)] or inflammation (hs-CRP, IL-6, and TNF-α)." (PMID 31068933, 2019). "Inflammatory cytokines such as tumor necrosis factor (TNF)-α are elevated inpreeclamptic women and are thought to be an important link between placentalischemia and endothelial dysfunction." (PMID 29898033, 2018). "Taken together, these findings suggest that elevated miR-21 expression contributes to TNF-α-induced endothelial dysfunction and the attenuating effects of DMY on TNF-α-induced HUVECs dysfunction depend on the repressing miR-21 expression." (PMID 29682517, 2018). "Taken together, these data demonstrated that miR-21-mediated DDAH1/ADMA/NO signal pathway plays an important role in TNF-α-induced endothelial dysfunction, and DMY attenuated endothelial dysfunction induced by TNF-α in a miR-21-dependent manner." (PMID 29682517, 2018). "In our research, we first elucidated the protective effects of TAS against TNF-α-triggered vascular endothelial cell damage and demonstrated that TAS prevented endothelial dysfunction through exerting anti-inflammatory and anti-apoptotic action." (PMID 30577658, 2018). "Inflammatory markers namely, TNF-α, IL-6 and AGP significantly and positively correlated with each other and with ET-1, a marker for endothelial dysfunction." (PMID 28344817, 2017). "IL-6 and TNF-α increase neutrophil superoxide anion generation that can inactivate eNO and prostacyclin (PGI2) resulting in endothelial dysfunction." (PMID 28824543, 2017). "The molecular targets through which aging perturbs vascular homeostasis are manifold and appear to include increased expression or activation of TNF-α, IL-1β, IL-6 family members and CRP, which promote inflammation and endothelial dysfunction." (PMID 28840062, 2017). "At conditions of endothelial dysfunction (ED), RES reduced the expression of cytokines, chemokines, ICAM and GM-CSF in TNF-α activated HUVECs, whereas eNOS expression was corrected to pre-ED homeostasis." (PMID 28610607, 2017). "In fact, overexpression of TNF-α in obese Zucker rats induces activation of NADPH oxidase and production of ROS, leading to oxidative stress and endothelial dysfunction." (PMID 26985993, 2016).
endothelial dysfunction (continued). "Vasocrine signaling by TNFα derived from periadventitial adipose tissue (PAAT) is also responsible for decreased NO production and endothelial dysfunction." (PMID 26578976, 2015). "VCAM-1 expression (a biomarker of endothelial dysfunction) was also induced by MRTF-A/B downregulation, although these effects were modest compared to those observed after TNF−α or LPS stimulation." (PMID 26024305, 2015). "Microalbuminuria as a marker of early renal damage reflects widespread vascular damage (microangiopathy), a pro inflammatory state (with increased levels of IL-6, TNF-α, CRP and fibrinogen) and ensuing endothelial dysfunction." (PMID 25971452, 2015). "To elucidate the source of increases in endothelial oxidative stress and the resulting endothelial dysfunction, we administered NOS inhibitor L-NAME, eNOS co-factor BH4, NADPH oxidases inhibitor apocynin, or peg-SOD in conjunction with TNFα treatment." (PMID 25874717, 2015). "TNF-α treatment significantly reduced the NO production by ECV304 cells, indicating that endothelial dysfunction had occurred." (PMID 25120637, 2014). "Furthermore, the numerous studies demonstrating improved endothelial function after anti-TNF-α therapy highlight the importance of these molecules in the pathogenesis of endothelial dysfunction and may lead the way toward advances in pharmacologic prevention of CVD in these populations." (PMID 24968272, 2014). "Our patients also had higher hs-CRP and IL-1, IL-6 and TNF-α concentrations than did control individuals, but these nontraditional cardiovascular risk factors did not fully account for the differences in biomarkers of endothelial dysfunction between patients and control individuals." (PMID 15899050, 2005). "Our objective was to determine the role of Interleukin-6 (IL-6) and Tumor Necrosis Factor-alpha (TNF-alpha), markers of immune activation and endothelial dysfunction, in patients with preeclampsia." (PMID 16259641, 2005). "Furthermore, activated leukocytes secrete inflammatory cytokines such as tumor necrosis factor (TNF) or IL-1, further exacerbating endothelial dysfunction progression." (PMID 40520933, 2025). "Previous clinical trials have shown that liraglutide reduced albuminuria, which is thought to be a biomarker of microvascular and macrovascular endothelial dysfunction, as well as circulating levels of various inflammatory markers, including CRP, TNF‐α and IL‐6 in individuals with type 2 diabetes." (PMID 40276845, 2025). "This is consistent with the known pathophysiology of hepatic IRI, where oxidative stress and the release of inflammatory mediators such as TNF-α, IL-6, and ICAM-1 lead to systemic endothelial dysfunction and infiltration of neutrophils in remote organs, including the lungs." (PMID 40429525, 2025). "Additional pro-inflammatory mediators, including TNF-α, IL-6, and IFN-γ, may further exacerbate endothelial dysfunction and microvascular inflammation." (PMID 40722702, 2025). "Although inflammatory mediators such as IL-6, TNF-α, and CRP are elevated across all three conditions, endothelial dysfunction and systemic cytokine signaling represent central converging mechanisms, linking local periodontal inflammation and metabolic dysregulation to cardiovascular complications." (PMID 41007869, 2025). "Adipose tissue, particularly visceral fat, becomes dysfunctional and secretes pro-inflammatory cytokines, including tumor necrosis factor-alpha (TNF-α), interleukin-6 (IL-6), and resistin, which promote hepatic fat accumulation, endothelial dysfunction, and vascular inflammation." (PMID 41020888, 2025). "Additionally, IL-8 correlates positively with TNF-α and VEGF, indicating a synergistic role in promoting endothelial dysfunction and oxidative stress." (PMID 40385768, 2025).
endothelial dysfunction (continued). "It is well established that EAT secretes pro-inflammatory cytokines (such as IL-1β, IL-6, and TNF-α) and pro-fibrotic adipokines (such as TGF-β), which exert paracrine effects on adjacent cardiomyocytes, promoting oxidative stress, endothelial dysfunction, and fibrosis." (PMID 41294813, 2025). "Elevated levels of IL-6, TNF-alpha, CRP, MCP-1, and endothelial dysfunction biomarkers such as oxidized HDL and soluble ICAM-1 supports the role of inflammation in the development and persistence of visceral adiposity and systemic inflammation in this population." (PMID 40722634, 2025). "TNF-α significantly improved the predictive ability of the model, with a hazard ratio (HR) of 2.5 (95% CI: 1.11–6.34; p = 0.01) for MACE in patients with TNF-α ≥ 5.19 pg/mL, even after adjusting for endothelial dysfunction and IL-6." (PMID 40310443, 2025). "TNF-α, by activating NF-κB signalling, increasing ROS production and up-regulating adhesion molecules, including ICAM-1 (Intercellular Adhesion Molecule-1) and VCAM-1 (Vascular Cell Adhesion Molecule-1), induces endothelial dysfunction." (PMID 41301783, 2025). "These conditions are associated with persistent immune activation and the production of pro-inflammatory cytokines, such as interleukin-6 (IL-6), tumor necrosis factor-alpha (TNF-α), and C-reactive protein (CRP), which exacerbate endothelial dysfunction and promote atherosclerotic plaque formation." (PMID 40001504, 2025). "Upon recruitment to inflamed endothelium via chemokines such as CXCL1 and CXCL8, neutrophils exacerbate vascular inflammation by releasing pro-inflammatory cytokines, including IL-1β, IL-8, and tumor necrosis factor-α (TNF-α), which amplify endothelial dysfunction and promote monocyte adhesion." (PMID 40217958, 2025). "Trauma triggers a systemic inflammatory response, characterized by the release of cytokines such as interleukin-6 (IL-6) and tumor necrosis factor-alpha (TNF-α), which contribute to endothelial dysfunction, increased vascular permeability, and myocardial inflammation." (PMID 40724554, 2025). "To summarize, we discovered that preincubation with AMI ameliorated TNF-α-induced ASMase/CER and MAPK activation, which efficiently inhibited monocyte/EC interactions induced by TNF-α and reduced subsequent endothelial inflammation and endothelial dysfunction." (PMID 36103099, 2024). "Altered expression levels of TNF-α have been observed in preeclampsia, and a rs3783605 SNP may influence TNF-α production, contributing to the immune dysregulation and endothelial dysfunction of this disorder." (PMID 39409189, 2024). "These pathways stimulate the release of proinflammatory cytokines and chemokines, such as interleukin-6 (IL-6) and tumor necrosis factor-alpha (TNF-α), which promote inflammation and endothelial dysfunction, recruit immune cells to the site of injury and exacerbate the inflammatory response." (PMID 39539435, 2024). "This process activates these immune cells and induces the release of additional pro-inflammatory cytokines, i.e., IL1α, IL1β, TNFα, IFNγ, and IL17, which may exacerbate endothelial dysfunction and contribute to the degradation of the endothelial glycocalyx." (PMID 39596318, 2024). "Also, reductions in the C-reactive protein (CRP), TNF-α, and IL-6 further illustrate the anti-inflammatory properties of GLP-1RAs, which play a crucial role in mitigating ischemia–reperfusion injury and endothelial dysfunction." (PMID 38675485, 2024).
endothelial dysfunction (continued). "Additionally, hypertension-induced vascular damage is often accompanied by increased expression of pro-inflammatory cytokines such as tumor necrosis factor-alpha (TNF-α) and markers of oxidative stress, which further exacerbate endothelial dysfunction." (PMID 39364422, 2024). "Chromium could also reduce reactive oxygen species (ROS) and TNF-α, inhibit the expression of NF-kB, and decrease the expression of vascular cell adhesion molecule 1 (VCAM-1), thereby improving endothelial dysfunction." (PMID 38730326, 2024). "NK cells promote vasoconstriction of arterioles and could dysregulate CD28 null (CD4+ and CD8+), producing pro-inflammatory cytokines (TNF-α, INF-γ, IL-2) involved in oxidative stress, endothelial dysfunction, and arteriolar rarefaction." (PMID 39234606, 2024). "Besides, PS inhibits nuclear factor-kappa B (NF-κB) and tumor necrosis factor-α (TNF-α), which are mediators of endothelial dysfunction." (PMID 39281275, 2024). "AKT1, TNF-α, VCAM1, ICAM1, and NOS3 might be the key targets of the anti-endothelial dysfunction activity of biochanin A, and the key pathways might be PI3K-Akt and TNF signaling pathways." (PMID 38195507, 2024). "We are aware that many mediators are present in the conditioned medium and may promote endothelial dysfunction; however, our findings clearly ascribe a role to IFN-γ and TNF-α in the attenuation of endothelial growth and in the induction of cell toxicity." (PMID 39199315, 2024). "The TNF-α upregulates miR-17 and miR-31 in human umbilical vein endothelial cells (HUVECs) in which the miR-17 inhibits the ICAM-1 expression in a negative feedback loop while miR-31 downregulates eNOS pathway resulting in endothelial dysfunction." (PMID 38909168, 2024). "This activation leads to the rapid release of cytokines such as tumor necrosis factor-alpha (TNF-α), interleukin-1 beta (IL-1β), interleukin-6 (IL-6), and interleukin-18 (IL-18), driving systemic inflammation and leading to endothelial dysfunction, tissue damage, and increased vascular permeability." (PMID 39594987, 2024). "In fact, increased levels of inflammatory mediators, such as interleukin-17 (IL-17), interferon-γ (INF-γ), and TNF-α, activated NADPH oxidases (Nox) enzymes and increased reactive oxygen species production, acting a pivotal role in the pathogenesis of arthritis and endothelial dysfunction." (PMID 39234606, 2024). "Monocyte-derived macrophages fail to eliminate the modified lipoproteins and transform into highly inflammatory foam cells, releasing Tumor Necrosis Factor-α (TNF-α) and interleukin-1β (IL-1β), exacerbating endothelial dysfunction and perpetuating the inflammatory response." (PMID 38993522, 2024). "Biochanin A possibly prevents endothelial dysfunction via a complex network structure with multiple targets and pathways, among which AKT1, TNF-α, NOS3, ICAM-1, and VCAM-1 may be the key targets, according to network pharmacological analysis results." (PMID 38195507, 2024). "In addition, TNF-α and NF-κB induce insulin resistance and amplify oxidative stress through the IKK-β pathway, leading to endothelial dysfunction in T2DM coronary arteries." (PMID 37660030, 2023). "Since TNF-α is an important inflammatory cytokine, this increase in TNF-α expression might also contribute to the development of endothelial dysfunction." (PMID 36658708, 2023). "In particular, tumor necrosis factor (TNF)-α, the key pro-inflammatory cytokine of IMIDs, upregulates arginase expression in the endothelial cells leading to impairment of nitric oxide-mediated vasodilation, and consequently to endothelial dysfunction." (PMID 37409280, 2023). "Elevated cytokines, such as interleukins (IL)-1,interferon (IFN)-γ, and tumor necrosis factor (TNF)-α, couldinduce endothelial dysfunction, activate platelets, recruit neutrophils, andeventually trigger a hypercoagulable state, leading to myocardial injury." (PMID 39076704, 2023).
endothelial dysfunction (continued). "Second, oxidative stress which is produced by repeated hypoxemia and episodes of apnea leads to endothelial dysfunction and the rise of proinflammatory chemical mediators, such as Cyclooxygenase (COX-2), tumor necrosis factor-α (TNF-α), Interleukins and other pro-inflammatory chemical mediators." (PMID 37416312, 2023). "Considering the increasing importance of endothelial dysfunction and leukocyte infiltration in the homeostasis of vascular tone and blood flow, we investigated the effect of FJH-KO on the expression of adhesion molecules and NF-κB signaling induced by TNF-α." (PMID 38139268, 2023). "Nevertheless, TNF-α inhibitors, which are commonly used for the treatment of IMIDs, decrease systemic inflammation and VEGF production, and thus have potential efficacy on endothelial dysfunction." (PMID 37409280, 2023). "In addition, it alleviated endothelial dysfunction, led to a decrease in serum E-selectin and ICAM-1, and decreased the level of pro-inflammatory cytokines IL-6 and TNF-α in the serum and MPO, as well as the MDA of the oxidative stress marker." (PMID 37371797, 2023). "Cytokines like tumor necrosis factor (TNF), Interleukin (IL)-1, IL-6, IL-8, IL-12 and IL-17 propagate the inflammatory response through leukocyte recruitment, release of secondary inflammatory mediators, endothelial dysfunction and NETs formation." (PMID 35757734, 2022). "Excess of UA has paradoxically pro-oxidant effects in the vascular cells, impaired nitric oxide production, increased cytokines (IL 1β, IL 6, TNF α, CRP, MCP-1), and platelet-derived growth factors expression, leading to endothelial dysfunction and VSMC proliferation." (PMID 36060948, 2022). "TNF-α is reported to trigger the interaction between monocytes and vascular endothelial cells, enhance the expression of adhesion molecules, such as VCAM-1, ICAM-1, and E-selectin, and finally induce endothelial dysfunction." (PMID 36278191, 2022). "Upon endothelial damage, there is an increase in proinflammatory molecules such as interleukin-1 (IL-1), interleukin-6 (IL-6), tumor necrosis factor alpha (TNF-α) and C-reactive protein (CRP) leading to a proinflammatory endothelium and endothelial dysfunction." (PMID 35455027, 2022). "Crosstalk between the pro-inflammatory TNF-α-NFκB signaling axis and the canonical Wnt/β-catenin signaling pathway potentially plays an important role in regulating endothelial dysfunction, though the exact nature of this is not defined." (PMID 36794234, 2022). "Moreover, SFN suppresses endothelial inflammation by preventing TNF-α-mediated secretion of VCAM-1, ICAM-1, E-selectin, Endothelin-1 as well as hyperglycemia-induced endothelial dysfunction." (PMID 33988232, 2021). "Oscillatory shear stress also promotes generation of reactive oxygen species and production of pro-inflammatory cytokines such as tumor necrosis factor-α (TNF-α) and interleukin-6 (IL-6), thereby further promoting endothelial dysfunction and formation of atherosclerotic plaque." (PMID 33875621, 2021). "Patients with MetS may also exhibit micro-albuminuria, endothelial dysfunction and a pro-inflammatory and pro-thrombotic state, with increased circulating C-reactive protein (CRP), tumor necrosis factor-α (TNF-α) and interleukin-6 (IL-6)." (PMID 33777773, 2021). "However, the RUPP model also mirrors increased Th1, Th17, and other PreE-associated molecular changes such as increased ET-1, AT1-AA, ROS, and TNF-α, as well as critical disease phenotypes (i.e., HTN, endothelial dysfunction)." (PMID 35096797, 2021). "In addition, it has been well documented that inflammatory factors such as IL-1β, TNF-α, TGF-β, and endotoxins can induce endothelial dysfunction via EndMT." (PMID 34604359, 2021).